IGF2 (insulin like growth factor 2)
Diseases named in the same sentence as IGF2 in open-access papers (continued):
Sharing a sentence is not in itself a finding about the gene and the disease.
colorectal cancer (92 papers, 2000 to 2026). A primary or metastatic malignant neoplasm that affects the colon or rectum. "In colorectal cancer, an IGF2 locus tandem duplication was found to be associated with a strong interaction between the IGF2 oncogene and a normally inaccessible super‐enhancer." (PMID 39853740, 2026). "It has been found that IGF2 is overexpressed in various types of cancer, including breast, prostate, and colorectal cancers, and is associated with chemotherapy resistance and poor prognosis." (PMID 39674501, 2025). "In protooncogenic cells, upregulation of IGF2 was associated with evasion of apoptosis, and IGF2 overexpression was associated with the development of colorectal carcinomas and activation of pAKT signaling." (PMID 40562100, 2025). "IGF2 has been used as part of a panel to test for CpG island methylator phenotype (CIMP) colorectal cancers which were associated with worse survival." (PMID 39068768, 2024). "A recent report has demonstrated that differences in IGF2 methylation in peripheral blood leukocytes can confer increased risk of colorectal cancer." (PMID 39068768, 2024). "In colorectal cancer, the most observed pathway changes are IGF2 overexpression and KRAS mutation which are located upstream in the PI3K/AKT pathway and activates them." (PMID 34572902, 2021). "Loss of imprinting (LOI) of IGF2 is considered to be an epigenetic marker for the risk of human cancer, particularly colorectal cancer and has a potential to affect the gene expression." (PMID 29017567, 2017). "For instance, overexpression of IGF2 promotes cell proliferation and invasion in colorectal cancer; high IGF2 expression is associated with poor clinical outcome in human ovarian cancer." (PMID 27895308, 2016). "In colorectal cancer, it has been reported that LOI of IGF2 occurs in 44% of informative colorectal cancers that are linked to microsatellite instability." (PMID 23171475, 2012). "LOI of IGF2 has previously been described in normal circulating peripheral blood lymphocytes of individuals with an increased risk to develop colorectal cancer." (PMID 23781309, 2012). "It has previously been reported that LOI for IGF2 is an epigenetic marker of colorectal cancer risk." (PMID 23781309, 2012). "Evidence for a crucial role of IGF-II for colorectal cancer development in humans stems from a report demonstrating overexpression of IGF-II in tumorous colonic tissue, as a consequence of loss of imprinting in the IGF2 gene." (PMID 17118177, 2006). "Specifically, in this region, IGF2 overexpression was found to be caused by hypomethylation, which acts as a risk biomarker for colorectal carcinoma due to its implication in tumorigenesis promotion, as well as in different stages of progression and metastasis." (PMID 32726996, 2020). "Cancer genome (CGA) data confirms this hypothesis, with at least 20% of all colorectal cancers having associated increased IGF2 expression." (PMID 31388182, 2019). "The IGF2 gene itself is associated with aggressive and chemotherapy resistant colorectal cancer." (PMID 31623387, 2019). "This epigenetic alteration was even described as a “manifestation or biomarker of colorectal cancer”, which means that detection of IGF2 loss of imprinting could serve as a valuable diagnostic tool." (PMID 31623387, 2019). "Loss of IGF2 imprinting in peripheral blood leukocytes may provide a potential biomarker for diagnosing individuals who have a high risk of colorectal cancer." (PMID 27275535, 2016). "However, a study on the loss of imprinting of the IGF2 gene in colorectal cancers has also shown a loss of imprinting in normal mucosa and peripheral blood leukocytes." (PMID 21375775, 2011). "It has been suggested that biallelic expression of imprinted genes such as IGF2 may be a useful predictive marker for risk of colorectal cancer development, even in other, unaffected tissues such as blood." (PMID 21042416, 2010).
colorectal cancer (continued). "LOI of IGF2 gene is an important cause of biallelic expression of IGF2 and has been reported in many different types of tumors including osteosarcoma, lung adenocarcinomas, head and neck squamous cell adenocarcinomas, Wilms'tumor, prostate cancer, and colorectal carcinomas." (PMID 19737423, 2009). "In colorectal cancer, PLAG1 is a gene directly targeted by miR-181a/135a/302c, and then affects the IGF2 signaling pathway, regulates the proliferation and drug resistance of colorectal cancer cells, and affects their sensitivity to 5-FU." (PMID 40276502, 2025). "In a mouse model, overexpression of IGF-2 leads to colorectal cancer, and the application of MEDI-573 effectively reduces the level of IGF-2 expression and inhibits the growth of colorectal tumor cells." (PMID 38331804, 2024). "Paracrine signals from CAFs are also mediated by IGF2 as, in fact, exposure of colorectal cancer cells to CAF-derived IGF2 increases the activation of the IGF1R and downstream signaling, including the Hippo–YAP1 pathway." (PMID 38892104, 2024). "IGF1R expression is significantly increased in colorectal cancer tissues and acts as a potent receptor in response to IGF2 stimulation leading to adverse outcomes." (PMID 38887298, 2024). "IGF2 is highly upregulated in CAFs of colorectal cancer compared to normal fibroblasts and has been described as a prominent secreted factor that significantly enhances growth, migration, and invasion of tumor cells in different cancers." (PMID 37566084, 2023). "CircEZH2/miR-133b/insulin like growth factor 2 mRNA binding protein 2 (IGF2BP2) aggravates colorectal cancer progression via enhancing the stability of m6A-modified CREB1 mRNA." (PMID 38023219, 2023). "Our study is in consistent with others observation that IGF1R inhibitor potentiates the efficacy of Anti-VEGF therapy against IGF2-Overexpressing colorectal cancer tumors." (PMID 35974000, 2022). "Recent preclinical evidence demonstrated that MEDI-573 induces apoptosis and inhibits tumor growth in a subset of colorectal cancer overexpressing IGF2." (PMID 34440844, 2021). "In colorectal cancer, tandem duplications include the IGF2 locus, TAD boundary, and a super-enhancer in adjacent TAD to mediate a de novo 3D contact domain between preexisting TADs, resulting in high-level overexpression of IGF2." (PMID 33168103, 2020). "Particularly, the role of IGF2 requires more research focused on more specialized adult tissues as well as carcinogenesis (including colorectal cancer)." (PMID 31623387, 2019). "Discovery of a connection between IGF2 LOI with colorectal cancer was a major success, with effects of this defect including IGF2 overexpression and, moreover, global chromatin instability, increased cell proliferation, and tumor development." (PMID 31623387, 2019). "According to the authors, both of these components of the IGF system (including IGF2) can serve as early indicators of impending colorectal cancer." (PMID 31623387, 2019). "A pilot study indicated a significant relationship between the LOI of IGF2 and the family as well as personal history of colorectal cancer." (PMID 31623387, 2019). "There is a discussion on the correlations between the degree of DNA methylation (hypo- and hypermethylation) of imprinting-associated IGF2/H19 domain DMR and IGF2 LOI in colorectal cancer and normal colon mucosa." (PMID 31623387, 2019). "It is worth mentioning that in colorectal cancer cell lines IGF2 overexpression regulates sensitivity and/or response to IR/IGF1R TKI." (PMID 31480557, 2019). "In another study on colorectal cancer, was observed that in tumor tissues the expression of both miR-483-3p/-5p and IGF2 was significantly up-regulated in more than 60% of cases with a concomitant positive correlation between the two genes." (PMID 29867024, 2018).
colorectal cancer (continued). "Reports that biallelic IGF2 expression in normal colonic mucosa and blood was severalfold more frequent in colorectal cancer patients than in healthy individuals have promoted the idea that LOI predisposes to cancer." (PMID 28854270, 2017). "Emerging evidence indicates that IGF2 plays an important role in various human malignancies, including colorectal cancer (CRC)." (PMID 27366946, 2016). "In this study, we investigated the overexpression of IGF2 intron-derived miR-483 in tissues and serums of CRC patients and explored the molecular mechanisms by which overexpressed miR-483 predisposes to colorectal cancer." (PMID 27366946, 2016). "Silencing of the IGF2 gene was recently reported to result in apoptosis only for IGF2 LOI colorectal carcinomas." (PMID 25364428, 2014). "Even single-copy gains in the AXI region were associated with strong induction of OVAL RNA, similar to e.g. IGF2 in colorectal cancer." (PMID 24265805, 2013). "Hypomethylation at the IGF2 DMR has been associated with an increased risk of developing cancers, such as Wilms' tumor, colorectal cancer and ovarian cancer." (PMID 23388414, 2013). "In this study, we constructed a novel replication-selective adenovirus based on the IGF2 LOI system to target colorectal cancers." (PMID 23171475, 2012). "Our aim was to investigate the feasibility of using the IGF2 imprinting system for targeted gene therapy of colorectal cancer." (PMID 23171475, 2012). "Tests based on analysis in adult blood samples of allelic expression of the imprinted IGF2 gene in the diagnosis of colorectal cancer have become the subject of commercial development." (PMID 21042416, 2010). "It has also been suggested that IGF-2 plays a role in the development of liver metastasis from colorectal cancer." (PMID 15785755, 2005). "IGF-2 and IGFBP-3, on the other hand, exhibited statistically significant, positive associations with colorectal cancer risk when cases were confined to those diagnosed within a relatively short time period after enrolment (within 8 years)." (PMID 11742490, 2001). "This is the first study to investigate the associations of IGF-1, IGF-2 and IGFBP-3 concentrations with the risk of colorectal cancer in prospectively collected blood samples from an Oriental population." (PMID 11742490, 2001). "In colorectal cancer, tandem duplications containing TAD boundaries are found to lead to de novo 3D contact domain formation between the cancer-associated locus (IGF2) and super enhancers in the preexisting TADs, resulting in >250-fold overexpression of IGF2." (PMID 39872109, 2023). "PLAGL2 was also reported to activate the IGF2 signaling pathway in colorectal cancer." (PMID 36437415, 2023). "Besides, dysregulation of miR-210-3p, miR-491-5p, and miR-615-3p contributes to the pathogenesis of atherosclerosis, colorectal carcinoma, and non-small lung cancer through modulation of IGF2 expression level (Liu j." (PMID 33768092, 2021). "In addition, LOI of IGF2 is an early event in colorectal cancer development, activating IGF1R and AKT1 signaling pathways." (PMID 31623387, 2019). "Additionally, the advisability of the use of anti-IGF2 in colorectal cancer in vivo needs to be determined." (PMID 31623387, 2019). "Therefore, we compared the therapeutic effect between IGF2 regulatory sequences and H101 for colorectal cancer treatment." (PMID 23171475, 2012). "In addition, IGF2 is known to be overexpressed in cancer and specifically, insulin signaling has been demonstrated to play a role in colorectal cancer." (PMID 21172019, 2010). "Methylation analysis of the IGF2 DMR0 has been carried out in many cancer studies following the demonstration that hypomethylation of this DMR is associated with loss of imprinting in Wilms tumour and colorectal cancer." (PMID 18365005, 2008).
colorectal cancer (continued). "For instance, LOI of the IGF2 (insulin-like growth factor 2) gene is seen in many patients with colorectal cancer, and biallelic expression of IGF2 is found in the normal-appearing colonic epithelium of colorectal cancer patients." (PMID 17592497, 2007). "Our second conclusion is that one of the growth factors, IGF2, may be of aetiological significance in colorectal cancer." (PMID 16804529, 2006). "IGF2 and ETV1 are well-known oncogenes, previously observed with focal amplification in colorectal cancer and as gene-gene fusion in prostate cancer, respectively." (PMID 32631391, 2020). "The IGF2 gene and IRS2 gene are frequently gained in colon cancer and have been proposed as a colorectal cancer ‘driver’ oncogenes." (PMID 31526479, 2019). "We obtained 401 colorectal cancer specimens and successfully quantified DNA methylation in eight CIMP-specific gene promoters (CACNA1G, CDKN2A, CRABP1, IGF2, MLH1, NEUROG1, RUNX3, and SOCS1) using MethyLight technology." (PMID 31690257, 2019). "In colorectal cancer (CRC), methylation and imprinting status of the IGF2/H19 domain have been studied." (PMID 30509319, 2018). "Taken together, our data demonstrated that miR-486-5p promotes colorectal cancer proliferation and migration through activation of PLAGL2/IGF2/β-catenin signal pathway, which is a promising therapeutic target of CRC treatment." (PMID 30305607, 2018). "In summary, our results show that an oncolytic adenovirus regulated by the IGF2 LOI system confers a significant anti-tumor effect by induction of apoptosis in vitro and in vivo in human colorectal cancer cells." (PMID 23171475, 2012). "In this study, semi-quantitative RT-PCR analyses of 48 paired, colorectal cancer patient samples showed significant overexpression of tumor IGF-1R and IGF-2 mRNA." (PMID 22159423, 2012). "For example, in a survey of 41 breast and 27 colorectal cancer cell lines, the expression levels of IGF-1R, IRS-1, IRS-2, and IGF-2 were correlated with positive predictive values for h10H5." (PMID 22952934, 2012). "In this study, we demonstrate a significant overexpression of IGF-1R, IGF-2 and MMP-7 mRNA in colorectal cancer tissues." (PMID 22159423, 2012). "The Laird methylation marker panel used to determine CIMP status of colorectal cancers consists of the CACNA1G, IGF2, NEUROG1, RUNX3 and SOCS1 genes." (PMID 20846368, 2010). "We obtained 920 colorectal cancer specimens and quantified DNA methylation in the 8 CIMP-specific gene promoters (CACNA1G, CDKN2A, CRABP1, IGF2, MLH1, NEUROG1, RUNX3 and SOCS1) by MethyLight technology." (PMID 17474983, 2007). "Our data thus suggest that circulating IGF-2 and IGFBP-3 can serve as early indicators of impending colorectal cancer." (PMID 11742490, 2001). "Both IGF2 and IRS4 were initially discovered by CESAM as enhancer hijacking target genes using CNV breakpoints profiled by microarray with much larger sample sizes (378 colorectal cancers and 497 lung squamous cell carcinomas)." (PMID 39051548, 2024). "In addition, recurrent focal genomic amplification spanning IGF2, WiNTRLINC1, and ASCL2 genes was detected in 9.9% of colorectal carcinomas and 2.7% of stomach adenocarcinomas." (PMID 34538872, 2021). "Consistently, positive regulators of Akt signaling, such as Akt (Z-score = 1.626, p = 1.18E–06), IGF2 (Z-score = 2.025, p = 4.70E–10), TGFA (Z-score = 2.251, p = 1.96E–04), and MAPK8 (Z-score = 2.231, p = 4.01E–05), were activated in recurrent colorectal cancers." (PMID 33425893, 2020). "This study aims to evaluate the role of IGF2 in colorectal carcinogenesis, as its etiological connection to many cancers was indicated and no review focused solely on colorectal cancer can currently be found." (PMID 31623387, 2019).
colorectal cancer (continued). "Moreover, also adult tumors are linked to genetic and epigenetic defects of this imprinted locus such as colorectal cancer (CRC), hepatocellular carcinoma (HCC) and breast cancer (BrCA) pointing out to IGF2 as the main oncogene of this genomic locus." (PMID 29867024, 2018). "Moreover, the methylation markers of MLH1, IGF2, and CACNA1G had a higher degree in the proximal colon cancer network compared with the distal colorectal cancer network." (PMID 28623901, 2017). "We examined the expression levels of miR-483-3p, miR-483-5p and IGF2 in 77 cases of primary colorectal cancers and their adjacent non-cancerous tissues by quantitative RT PCR." (PMID 27366946, 2016). "IGF2 knockdown significantly reduced the CD133+ cell population in HCT116 CSCs, suggesting that IGF2 is a critical growth factor in maintaining self-renewal of CSCs in colorectal cancer cells." (PMID 27275535, 2016). "Similarly, IGF2 LOI has been reported in a variety of human cancers at widely varying rates, including Wilms' tumor, colorectal cancer, hepatoma, lung cancer, ovarian cancer, bladder cancer, leiomyosarcoma, and esophagus cancer." (PMID 27275535, 2016). "IGF-1, IGF-2 and IGFBP-3 were measured in the serum of 135 men who developed colorectal cancer over 12 years of follow-up and 661 control subjects drawn from the cohort, who were matched to the index cases by neighbourhood of residence, age, and year and month of sample collection." (PMID 11742490, 2001). "For instance, in colorectal cancer, recurrent tandem duplications intersecting with TAD boundaries result in the formation of new 3D contact domains, encompassing insulin-like growth factor 2 (IGF2) and a lineage-specific SE, leading to high-level gene activation." (PMID 40032852, 2025). "Likewise, in colorectal cancer tissues, it has been demonstrated that the hypomethylation of a “differently methylated region” (DMR), located adjacent to IGF2, might occur concurrently with IGF2 LOI, contributing to IGF-2 upregulation." (PMID 36901760, 2023). "While there are some reports on the use and effects of insulin/IGF-targeting trials in colorectal cancer, there is not much published data regarding the effect of the CRC treatment using precise anti-IGF2 approaches." (PMID 31623387, 2019). "Importantly, the methylation status of one of these elements (IGF2-DMR; located in the last exon of IGF2 and normally only methylated on the paternal allele) has been reported to be associated with the risk of developing human colorectal cancer in some studies but not in others." (PMID 21991322, 2011). "Utilizing MethyLight technology (real-time PCR), we quantified DNA methylation in 8 CIMP-specific promoters {CACNA1G, CDKN2A (p16), CRABP1, IGF2, MLH1, NEUROG1, RUNX3 and SOCS1} in 758 non-MSI-high colorectal cancers obtained from two large prospective cohorts." (PMID 17474983, 2007).